NLRP3 (NLR family pyrin domain containing 3)
Diseases named in the same sentence as NLRP3 in open-access papers (continued):
Sharing a sentence is not in itself a finding about the gene and the disease.
Hypertension (continued). "Our next step sought to determine whether the anti-NLRP3 therapy could decrease cascade reaction of inflammation, regulate neurotransmitters, and counteract hypertension." (PMID 29573749, 2018). "We found that blockade NLRP3 therapy markedly reversed hypertension, in consistent with the results reported by Krishnan, as well as significantly reduced NLRP3 pathway protein expression, decreased PICs, CCL2, CXCR3, and VCAM-1, adjusted TH, GAD67, and GABA in PVN and plasma NE." (PMID 29573749, 2018). "Furthermore, the effects of NLRP3 gene silencing on hypertension and vascular remodeling were investigated in SHR." (PMID 28981106, 2017). "NLRP3 inflammasome plays an important role in hypertension and vascular remodeling." (PMID 28981106, 2017). "The produced ROS leads to activation of the NLRP3 inflammasome, resulting in activation of caspase-1, cleavage of pro-IL-1β and pro-IL-18, and the production of active forms of IL-1β and IL-18, which increase the inflammatory response, fibrosis, and vascular remodeling in hypertension." (PMID 40227195, 2025). "Therefore, investigating the role of the NLRP3 inflammasome in hypertension and kidney injury could provide valuable insights." (PMID 39576390, 2025). "The finding that a 1 ng/mL increase in serum NLRP3 raises the odds of hypertension 1.6 times is statistically significant (controlling for confounding variables) and supports the hypothesis that the pro-inflammatory marker NLRP3 plays a role in the pathogenesis of hypertension." (PMID 40572711, 2025). "Therefore, exercise may raise β-OHB levels and subsequently inhibit renal NLRP3 inflammasome activation, thereby alleviating hypertension and preserving kidney function." (PMID 38681198, 2024). "Moreover, salt-induced hypertension in rats occurs partly because of NLRP3 inflammasome activation." (PMID 37226086, 2023). "Thus, in Ang II-induced hypertension, Ang II downstream mechanisms promote inflammatory cell infiltration, proinflammatory cytokine release and the activation of the NLRP3 inflammasome, which further induces inflammatory reactions leading to the development and progression of renal tissue injury." (PMID 37511174, 2023). "Therefore, MMF may inhibit elevation of NLRP3 via attenuation of these pro-inflammatory cytokines and NF-κB activation in Ang II-dependent hypertension." (PMID 35887028, 2022). "Moreover, the level of IL-6, instead of IL-1β, decreased in NLRP3-/- mice, which means that NLRP3 is widely involved in diverse inflammatory responses, and anti-NLRP3 treatment would receive further benefits of relieving auto-inflammation in hypertension pathogenesis." (PMID 36204568, 2022). "Additionally, we speculated that miR-135a-5p inhibits TXNIP to affect the binding of TXNIP to NLRP3, thus participating in hypertension-induced cardiac fibrosis and inflammation." (PMID 35148667, 2022). "In addition to inhibiting NF-κB, direct inhibiting IL-1β, the central pro-inflammatory cytokine in NLRP3 pathway, also obtained the results of attenuating hypertension by the activation of renin-angiotensin system and the generation of ROS in paraventricular nucleus." (PMID 36204568, 2022). "Therefore, we questioned whether there was a link between the NLRP3 inflammasome and vascular endothelial damage in hypertension." (PMID 33633569, 2020). "Moreover, a fundamental role of the NLRP3 inflammasome was confirmed in hypertension." (PMID 32545788, 2020). "Furthermore, during non-pregnant conditions, infusion of AngII induces hypertension with activation of NLRP3 inflammasome in the aorta, and NLRP3 deficiency attenuated AngII-induced hypertension via inhibition of NLRP3 inflammasome activation in mice." (PMID 32161574, 2020). "Therefore, inhibitors of NLRP3 could be a very effective treatment of pregnancy-induced hypertension and preeclampsia." (PMID 32650532, 2020).
Hypertension (continued). "However, the activation mechanisms of the NLRP3 inflammasome complex and its roles in aortic remodeling in hypertension are largely unknown." (PMID 30906225, 2019). "Furthermore, it has been shown that SGK1 contributes to cardiac inflammation and fibrosis by mediating nucleotide-binding oligomerization domain-like receptor with pyrin domain 3 (NLRP3) inflammasome activation, and cardiac fibroblast-to-myofibroblast transition in AngII-induced hypertension." (PMID 30524295, 2018). "However, the role of intracellular NOD like receptors, such as pyrin domain containing 3 (NLRP3) in hypertension remains unknown." (PMID 29573749, 2018). "Furthermore, we postulated that blockade of NLRP3 in PVN could have important functional consequences and lead to an associated decrease in hypertension by regulating inflammation microenvironment and neurotransmitters." (PMID 29573749, 2018). "Thus, an NFκB inhibitor BAY11-7082 was used to determine whether NFκB signaling in VSMCs would contribute to NLRP3 inflammasome activation and phenotypic transformation in hypertension." (PMID 28981106, 2017). "NLRP3 may be a critical target for attenuation of chronic vascular inflammation in hypertension." (PMID 28981106, 2017). "NLRP3 may be a novel target for the intervention of hypertension and vascular remodeling." (PMID 28981106, 2017). "We performed multivariate binary logistic regression in the groups (outcome variable: hypertension vs. non-hypertension) with variables identified as significantly different: VLDL, triglycerides, CRP, WBC, NLRP3 (serum), and IL-1β B (saliva)." (PMID 40572711, 2025). "Studies have shown that genetic knockout of NLRP3 or ASC prevents blood pressure elevation in the two-kidney, one-clip (2K1C) model of hypertension in mice." (PMID 40433411, 2025). "Moreover, recent studies provide compelling evidence that the NLRP3 inflammasome plays a pivotal role in sodium reabsorption in the renal tubules and may thereby contribute directly to the pathogenesis of hypertension through the action of its downstream pro-inflammatory cytokines, IL-1 and IL-18." (PMID 40867825, 2025). "In addition, it has also been demonstrated that inhibition of the inflammatory response or NLRP3 gene deletion improved cardiac remodeling and reduced proinflammatory cytokines secretion and fibrotic processes, as well as attenuated angiotensin II (Ang II)-induced hypertension." (PMID 39403576, 2024). "NLRP3 gene deletion attenuates Ang II-induced inflammation, VSMC phenotypic transformation and proliferation, and Ang II-induced hypertension and vascular remodeling." (PMID 35295586, 2022). "After 12 weeks of EOJ consumption, four genes related to hypertension (PTX3, NLRP3, NPSR1 and NAMPT) were differentially expressed in peripheral blood mononuclear cells (P < 0.05)." (PMID 32661681, 2021). "Currently, studies on the impact of TGF-beta-mediated inflammation on renal diseases are mainly focused on hypertension, and reports on TGF-beta-mediated NLRP3 inflammasomes and renal fibrosis are limited." (PMID 32117956, 2020). "The results indicate that the HAT activation and the following NFκB and NLRP3 inflammasome activation are important contributors in the VSMC phenotypic transformation and proliferation in hypertension." (PMID 28981106, 2017). "Both in vivo and in vitro studies showed that the NLRP3 is critical in the development of vascular inflammation and VSMC phenotypic transformation in hypertension." (PMID 28981106, 2017). "In conclusion, NLRP3 inflammasome is a critical positive regulator of VSMC phenotypic transformation and proliferation in hypertension." (PMID 28981106, 2017). "In the NLRP3-/- mice, hypertension was avoided, but in the ASC-/-mice, there was no discernible reduction in blood pressure." (PMID 40079000, 2025). "We found significant differences in serum NLRP3 levels between patients with and without hypertension, with higher levels in hypertensive individuals (p = 0.001)." (PMID 40572711, 2025).
Hypertension (continued). "The NLRP3 inflammasome, a member of the NOD-like receptor family containing a pyrin domain, exerts a prominent effect in vascular inflammatory processes, playing a crucial role in hypertension-related vascular inflammation." (PMID 39974735, 2025). "Inhibition of NF-κB could attenuate the expression levels of NLRP3, and the expression of IL-1β, and reduce oxidative stress in PVN, then improve hypertension." (PMID 36771206, 2023). "Moreover, rutin, a flavonol present in CV extracts, has been documented to prevent hypertension and vascular complication by modulating NOX4 and ROS-sensitive NLRP3 inflammasome as a result of its antioxidant and anti-inflammatory action." (PMID 37215635, 2023). "It has also been demonstrated that the absence of ASC, a component of the NLRP3 inflammasome, reduces hypoxia-induced hypertension." (PMID 37226086, 2023). "Despite the evidence reviewed above describing activation of the NLRP3 inflammasome in the kidneys during hypertension, there is a lack of information in the literature regarding the presence of renal pyroptosis in the hypertensive setting." (PMID 33494430, 2021). "The NLRP3 inhibitor, MCC950, can attenuate inflammation and hypertension in mice." (PMID 34485175, 2021). "In VSMCs, CRID3 inhibited collagen synthesis induced by Ang II and CRID3 prevented the increased expression of MMP2 and MMP9 unlike TIMP2, indicating that suppressing NLRP3 inflammasome was a target in aortic fibrosis in hypertension." (PMID 30906225, 2019). "We recently showed that treatment of mice with MCC950, a selective NLRP3 inflammasome inhibitor, can reverse one kidney/DOCA/salt-induced hypertension in adult mice, implicating a role for inflammasomes in at least one form of hypertension." (PMID 28659507, 2017). "There was also evidence of inflammation of renal and brain tissue, but an inhibitor of the NLRP3 inflammasome did not affect Ang II-induced hypertension in aged mice." (PMID 28659507, 2017). "However, the role of CaSR-mediated NLRP3 inflammasome activation in hypertension has not yet been investigated." (PMID 38715976, 2024). "Moreover, in the deoxycorticosterone acetate (DOCA)/salt-induced hypertension model, the levels of the 32-residue hormone peptide ELABELA are decreased, promoting the activation of NOXs that generates ROS, and subsequently, NLRP3 inflammasome activation in the renal medulla and renal cortex." (PMID 35204131, 2022). "Collectively, this work shows that the WNK1 pathway has a critical function in suppressing NLRP3 activation and suggests that pharmacological inhibition of this pathway to treat hypertension might have negative clinical implications." (PMID 34315884, 2021). "As the NLRP3 inflammasome is activated in both hypertension and end stage renal disease (ESRD), we speculated that the extent of NLRP3 inflammasome activation may be different in patients with apparent hypertension and hypertensive, multi-morbid hemodialysis (HD) patients." (PMID 33114648, 2020). "However, the increase of Ang II and the sympathetic outflow are not all processes participating in the development of NLRP3 inflammasome-induced hypertension." (PMID 32650532, 2020). "Ang II could induce hypertension during pregnancy in ASC−/− mice but not in NLRP3−/− mice, suggesting that NLRP3 contributes to hypertension independently of the inflammasomes." (PMID 30906225, 2019). "However, here we found that MCC950 did not affect blood pressure in aged mice when co-infused with Ang II, suggesting that NLRP3 inflammasome activity does not contribute to the increased pressure seen in this form of hypertension." (PMID 28659507, 2017). "Our laboratory has reported that treatment with MCC950, a selective NLRP3 inflammasome inhibitor, can reverse deoxycorticosterone acetate (DOCA) salt-induced hypertension in mice, implicating a role for inflammasomes in the development of at least one form of hypertension." (PMID 28659507, 2017).
Hypertension (continued). "Whether hypertension induced by dietary Mg2+ depletion is dependent upon activation of the NLRP3 inflammasome or production of IsoLGs was not examined, but these findings are consistent with a contribution of Mg2+ depletion to hypertension-promoting inflammation." (PMID 38665599, 2024). "However, the mechanism of NLRP3 activation in pregnancy-induced hypertension has not been reported." (PMID 37024673, 2023).
injury (158 papers, 2015 to 2026). Damage inflicted on the body as the direct or indirect result of an external force, with or without disruption of structural continuity. "Activation of NLRP3 inflammasome is involved in microglial cell activities in hippocampus, thus causing damage in a rat model of traumatic brain injury." (PMID 31383789, 2019). "Therefore, underlying mechanism of the NLRP3 inflammasome in the development of CNS trauma has attracted much attention." (PMID 35186932, 2022). "Furthermore, the activation of NLRP3 is closely associated with secretion of mature-IL-1β and cleave-caspase-1, which are closely related to the pathogenesis of liver injury." (PMID 33364966, 2020). "For example, NLRP3 inflammasome activation initiated by death-associated protein kinase (DAPK) or mitochondrial reactive oxygen species (mtROS) played a key role in causing acute lung injury, acute kidney injury, and long-term cognitive impairment due to paraquat exposure." (PMID 33912556, 2021). "This is achieved through the regulation of the NF-κB/NLRP3/caspase-1 signaling pathway, highlighting the potential of Salidroside as a preventative therapy for such environmental lung injuries." (PMID 41292520, 2025). "PFD + LIR treatment significantly reduced CTSB expression, consistent with prior findings that CTSB release activates NLRP3 following liver injury." (PMID 41413484, 2025). "Studies have shown that Ginsenoside Rg1 can inhibit the NLRP3 inflammasome by inducing autophagy, thereby alleviating acute liver injury." (PMID 40535916, 2025). "A study on acute lung injury revealed that PGK1 promotes M1 macrophage polarization by regulating NLRP3, thereby participating in the pathophysiology of acute lung injury." (PMID 40177399, 2025). "In myocardial ischaemia-reperfusion injury, miR-30a-5p exacerbates myocardial damage through the circ_0002612/miR-30a-5p/Ppargc1a/NLRP3 axis, while its inhibition can enhance mitochondrial function by activating SIRT1." (PMID 40504789, 2025). "Another study showed that dynasore greatly inhibited the NF-κB signaling pathway, activated the NLRP3 inflammasome, leading to mitigated LPS-induced acute lung injury in a mice model." (PMID 40374526, 2025). "In a similar fashion, ticagrelor, beyond its antiplatelet effect, reduced macrophage NLRP3 in vitro in acute coronary syndrome patients, and following myocardial ischemia reperfusion-induced acute lung injury in rats." (PMID 40622464, 2025). "HO-1 is reported to have antioxidant and anti-inflammatory effects in acute lung injury, and also can decrease NLRP3 inflammasome deactivation induced by heme." (PMID 38708425, 2024). "A recent study has reported that glyburide blocked the assembly and activation of NLRP3 inflammasome and IL-1β release by dampening the binding of NEK7 to NLRP3 in ventilator-induced lung injury." (PMID 38892264, 2024). "The NLRP3 inflammasome pathway is a key component of the immune system that can contribute to inflammatory responses in various diseases, including kidney injury." (PMID 39045044, 2024). "The protective effects were also induced by CHBP on decreasing the formation of NLRP3 inflammasome and the secretion of IL‐1β via the NF‐κB pathway in LPS‐induced acute lung injury." (PMID 39584501, 2024). "PGC-1α inhibited the activation of the NLRP3 inflammasome by protecting mitochondrial function, which was characterized in other diseases, such as kidney injury and demyelinating disorders." (PMID 37020714, 2023). "NLRP3 inflammasome is a well-known inflammasome mainly found in monocytes and macrophages and can mediate kidney injury." (PMID 37605037, 2023). "MCC950, a well-characterized, selective small molecule inhibitor of NLRP3 inflammasome activation was advanced to the clinic, but its development was terminated due to drug induced liver injury (DILI) detected at a daily dose of 1200 mg52." (PMID 37598239, 2023).